S100A8 (S100 calcium binding protein A8)
Diseases named in the same sentence as S100A8 in open-access papers (continued):
Sharing a sentence is not in itself a finding about the gene and the disease.
Obesity (continued). "For obesity, diabetes, hypertension and hyperlipidemia, the AUC values of S100A8 were 0.925 (95% confidence interval: 0.783–1.0), 0.875(95% confidence interval: 0.679–1.0), 0.96 (95% confidence interval: 0.849–1.0), 0.75 (95% confidence interval: 0.541–0.959), respectively." (PMID 37497233, 2023). "Importantly, it has been suggested that S100A8 would be a good target against obesity-induced chronic inflammation." (PMID 36235175, 2022). "Since M1/M2 transition is a crucial step during tissue repair we compared S100A8 and S100A9 during skin wound healing in wildtype mice and in db/db mice, the latter representing an established model of obesity-associated impaired wound healing with disturbed macrophage differentiation." (PMID 35198063, 2022). "Regarding the activation of macrophages, Saa3 has been shown to promote the infiltration of macrophages in adipose tissue, while S100a8 plays a central role in obesity-promoting macrophage-based inflammation and induces the secretion of cytokines from mononuclear cells." (PMID 35295992, 2022). "In humans, plasma S100A8/A9 levels have been correlated to insulin resistance and obesity." (PMID 31941045, 2020). "Importantly, CXCL1, S100A8, and NOD2 were also found to be positively associated with obesity in our murine study." (PMID 33123173, 2020). "It is therefore likely that IL-1β signaling from ATMs could also potentiate trained immunity within the context of obesity and that S100A8/A9 may therefore play a role in trained immunity upstream of IL-1β." (PMID 31249530, 2019). "Together, this suggests that, while S100A8/A9 plays an important role in inducing IL-1β production, additional inflammatory signals within the adipose tissue likely co-signal to promote IL-1β and myelopoiesis in obesity." (PMID 31249530, 2019). "This production of CD11c+ ATMs could also feed-forward to enhance the IL-1β signaling induced by S100A8/A9 in obesity to promote myelopoiesis and monocytosis." (PMID 31249530, 2019). "Our results indicated that these bone marrow-derived cells may be recruited from the circulation into lung tissue by lung stromal cells in obesity through locally elevated CSF2 as well as S100A8, which has been shown to promote accumulation of myeloid lineage cells at metastatic sites in vivo." (PMID 33670906, 2021). "HMGB1 released by necrotic adipocytes interacts with RAGE, inducing pro-inflammatory cytokines and ROS;S100A4, S100A8/A9, and S100B induce inflammation, interacting with RAGE;AGE accumulation in adipose tissue may contribute to obesity-associated insulin resistance." (PMID 34204735, 2021). "We selected five of these (ACACA, CETP, CTGF, S100A8, S100A9) for further analyses based on reported adipose or adipocyte gene expression changes in response to weight loss/dietary intervention (ACACA, CETP, CTGF), and/or associations with obesity or related traits (GWAS, and/or other literature)." (PMID 25651499, 2015). "Regarding intestinal dysfunction markers, both groups of patients with obesity showed higher circulating levels of LPB (P < 0.01), lactoferrin (P < 0.05 for OB-NG and P < 0.01 for OB-T2D) and S100A8 (P < 0.01)." (PMID 38315242, 2024). "So, some researchers have even proposed S100A8 as a novel marker of obesity in non-type 2 diabetics." (PMID 37497233, 2023). "For example, upregulation of S100A11 and S100A8 expression was observed in the liver of NAFLD patients and various mouse models of obesity and/or steatosis, as well as in hepatocytes exposed to fatty acids, thus suggesting a strong implication of these two S100 isoforms in NAFLD development." (PMID 36232334, 2022). "Morbid obesity, regardless of the degree of insulin resistance, was associated with changes in the expression of genes involved in pro- (such as CD86 and S100A8) and anti-inflammatory (such as CCL18 and ZBTB16) responses." (PMID 35625760, 2022). "We found that the high expression of S100A8 and S100A9 was related to obesity." (PMID 34055926, 2021).
Obesity (continued). "Alongside S100A8/A9, a number of endogenous TLR-4 ligands including gut-derived LPS, HMGB1, and modified LDL are elevated in the plasma and adipose tissue in obesity and may contribute to ATM priming to produce IL-1β." (PMID 31249530, 2019). "One study found that in obese individuals, the methylation levels of the S100A8 and S100A9 genes exhibit a negative correlation with their expression levels, which is closely associated with the pathological mechanisms underlying obesity." (PMID 40702573, 2025). "Increased concentration of S100A8/A9 (calprotectin) in serum has been observed in patients with coronary artery disease and may act as a serum biomarker of obesity in patients without type 2 diabetes." (PMID 36235175, 2022). "Moreover, compared with non-obese healthy individuals, the level of plasma S100A8/A9 in obese individuals is higher, which suggests that S100A8/A9 can also be a new marker of obesity in non-type 2 diabetes mellitus." (PMID 29942307, 2018). "S100A8 mRNA levels in skeletal muscle were not influenced by obesity or T2D." (PMID 19823685, 2009). "Plasma calprotectin and skeletal muscle S100A8 mRNA levels were measured in a cohort consisting of 199 subjects divided into four groups depending on presence or absence of type 2 diabetes (T2D), and presence or absence of obesity." (PMID 19823685, 2009).
pancreatic cancer (43 papers, 2012 to 2025). "The S100A8/S100A9 secreted by monocytes regulated the behavior of pancreatic cancer cells by causing a pre-metastasis cascade related to cancer spread." (PMID 35651786, 2022). "In summary, our data suggest the existence of paracrine feedback loop between stroma-associated S100A8/A9-secreting cells and pancreatic tumour cells." (PMID 30558665, 2018). "A significantly higher serum level of S100A8 in pancreatic cancer patients with cachexia patients appeared, indicating S100A8 can play an atrophic role in pathogenic development." (PMID 38361783, 2024). "Overall, our study provides valuable insights into the critical role of CD74 in regulating the oncogenic properties of pancreatic cancer cells and its influence on the expression and secretion of S100A8 and S100A9." (PMID 37629174, 2023). "Pancreatic cancer cells stimulated by S100A8 and S100A9 increased the secretion of pro-inflammatory cytokines IL-8, TNF-α and FGF." (PMID 35651786, 2022). "The proteins S100A9 and S100A8 are involved in a paracrine feedback loop between pancreatic cancer cells and monocytes." (PMID 35646116, 2022). "S100A8/A9 secreted by monocytes can induce pancreatic tumor cells to secrete proinflammatory cytokines, including IL-8, fibroblast growth factor (FGF), and tumor necrosis factor-alpha (TNF-α), mediated in part by RAGE in pancreatic tumor cells." (PMID 34527585, 2021). "Like other S100 proteins, binding and activation to the RAGE receptor by S100A8/A9 and subsequent activation of NF-κB in a positive feedback loop has been discussed as one of their major implications in pancreatic cancer progression." (PMID 32503348, 2020). "High expression of S100A8 and S100A9 was found in the stroma cells, mainly monocytes, of pancreatic cancer, and the number of S100A8 positive stroma cells correlated with the Smad4 status of the tumour." (PMID 32722137, 2020). "For patients with pancreatic cancer, release of S100A8/A9 proteins from myeloid cells increases CD33+CD14−HLA-DR− myeloid-derived suppressor cells." (PMID 30558665, 2018). "We previously showed that the stromal compartment of colorectal and pancreatic cancers contain CD14+ monocytic cells expressing S100A8 and S100A9 proteins." (PMID 30558665, 2018). "In the current study, we show that exposing monocytes to pancreatic tumour cell-derived conditioned media increased the expression of both S100A8 and S100A9." (PMID 30558665, 2018). "Stimulation of cultured pancreatic cancer cells with S100A8 and S100A9 increased the secretion of the pro-inflammatory cytokines IL-8, TNF-α, and FGF." (PMID 30558665, 2018). "Secreted S100A8/A9 from monocytes, in turn, led to secretion of several cytokines from pancreatic tumour cells." (PMID 30558665, 2018). "TGFβ1 and S100A8/A9, which share their overall effects on pancreatic cancer cells, mainly inhibit NF-κB and PI3K/AKT in a SMAD4-dependent manner." (PMID 27655713, 2016). "The expression levels of S100A8 or the heterodimer, S100A8/A9, are increased in tumor cells in multiple types of cancer, including gastric, colon and pancreatic cancer, but rarely in RCC." (PMID 25673070, 2015). "A reduced expression of CTLA4 among splenic MDSCs was observed in PDAC patients and was demonstrated to be consequent to the direct exposure of myeloid cell to pancreatic cancer derived products and in particular to the S100A8/A9 complex." (PMID 23359812, 2013). "The other study revealed that the ratio of S100A9- and S100A8- positive cells in the stroma was affected by the status of tumor suppressor protein Smad4 in corresponding pancreatic cancer cells." (PMID 22838504, 2012).
pancreatic cancer (continued). "Furthermore, CD74 was shown to promote a pro-inflammatory tumor microenvironment in pancreatic cancer by inducing the secretion of S100A8/A9 via activation of TRAF6-NF-κB." (PMID 39425000, 2025). "Therefore, this study involves the identification of various overexpressed protein members of the S100 protein family, including S100-A4, S100-A6, S100-A8, S100-A9, and S100-A11, to develop a successful multiepitope-based vaccine against pancreatic cancer." (PMID 38976715, 2024). "Therefore, our data indicate that both CD74 and S100A8 play crucial roles in determining the prognosis of patients with pancreatic cancer." (PMID 37629174, 2023). "In support of this hypothesis, S100A8 has been shown to stimulate the migration of pancreatic cancer cells in vitro." (PMID 37627239, 2023). "Moreover, genome-wide expression profiling of JHDM1D-AS1 expressing pancreatic cancer cells in mouse tumor xenografts showed increased expression of inflammatory response genes S100a8 (or Mrp8) and S100a9 (or Mrp14)." (PMID 35903199, 2022). "Hence, targeting S100A8/A9 represents a potential therapeutic option to curtail the aggressive nature of pancreatic cancer." (PMID 30558665, 2018). "The reduced CTLA4 expression found among splenic IMCs of PDAC patients was demonstrated to characterize an immune suppressive phenotype and to be consequent to the direct exposure of myeloid cells to pancreatic cancer derived products, S100A8/A9 complex in particular." (PMID 23359812, 2013). "Next, we investigated whether S100A8/A9 were overexpressed in pancreatic tumor tissues." (PMID 37629174, 2023). "The aim of the present study was to improve our understanding of the way in which EGF governs the pancreatic cancer cell response to relevant stromal derived molecules, TGFβ1 and S100A8/A9, while also investigating whether SMAD4 participates in this complex scenario." (PMID 27655713, 2016). "In summary, we demonstrate that CD74 regulates the expression and secretion of S100A8 and S100A9 and that these cytokines are clear prognostic markers in pancreatic cancer." (PMID 37629174, 2023). "As both S100A8/A9 are prognostic markers for patients with pancreatic cancer, with those with a higher expression having a poorer OS, we believe that the expression levels of both CD74 and S100A8/A9 can also be crucial prognostic markers in PDAC." (PMID 37629174, 2023). "We also reported that exogenously added S100A8 and S100A9 proteins enhanced the migration and proliferation of colorectal and pancreatic cancer cells in culture." (PMID 30558665, 2018). "In the current study, we found that S100A8 and S100A9 proteins influenced cytokine secretion from pancreatic cancer cells in overlapping but also distinct ways." (PMID 30558665, 2018). "Elevation of LRG1, SPARCL1, S100A8, Plastin-2 may be of special significance in a small but significant percentage of patients which have increased risk for prolonged development of a disease spectrum that connects AP, RAP, and chronic pancreatitis with emergence of pancreatic cancer." (PMID 30214418, 2018). "We next investigated downstream mediators of S100A8 and S100A9 signalling in pancreatic cancer cells, including phospho-MAPK proteins and NF-κB." (PMID 30558665, 2018). "In agreement with their likely infiltration, we found upregulation of the S100A8/A9 complex, an inflammatory mediator of immune suppression by MDSCs in PDL1-upregulated pancreatic cancers." (PMID 27589570, 2016). "We then investigated whether S100A8 and S100A9 could function as prognostic markers of pancreatic cancer." (PMID 37629174, 2023). "Our observation that S100A8 and S100A9 transcripts were detected in the eight cancer cell lines, and not in the HPNE control cell line, suggests that these two S100s also act directly on pancreatic cancer cells." (PMID 37627239, 2023).
pancreatic cancer (continued). "For instance, S100A8 and S100A9 enhance the production of IL-8 in pancreatic tumor cells, which could promote the accumulation of immunosuppressive myeloid cells, including MDSCs." (PMID 34187428, 2021). "Smad4 is a key mediator for TGFβ, a pro-apoptotic protein involved in pancreatic tumour progression, and tumours without Smad4 expression showed a decreased number of S100A8+ stroma cells." (PMID 32722137, 2020). "Conversely, pancreatic cancer cell-derived conditioned media and the individual cytokines, TNF-α and TGF-β induced the expression of S100A8 and S100A9 proteins in the HL-60 monocytic cell line and primary human monocytes, while FGF and IL-8 induced the expression of S100A9 only." (PMID 30558665, 2018). "S100A8 and S100A9 activated MAPK and NF-κB signalling in pancreatic cancer." (PMID 30558665, 2018). "However little is known about S100A8 and S100A9-mediated cross talk between stromal monocytes and pancreatic cancer cells." (PMID 30558665, 2018). "We investigated whether chronic exposure to EGF modifies in a SMAD4-dependent manner pancreatic cancer cell signalling, proliferation and invasion in response to EGF, TGFβ1 and S100A8/A9." (PMID 27655713, 2016). "Further endpoints were to assess whether pancreatic cancer cells are able to expand MDSCs in vitro and to evaluate the role of the inhibitory co-stimulatory molecules PDL1 and CTLA4 searching also for any potential effect of the S100A8 and S100A9 molecules." (PMID 23359812, 2013). "We report here a RAGE-dependent increase in levels of phosphor-Erk1/Erk2 and phospho-p38 phosphorylation following S100A8 and S100A9 treatment of pancreatic cancer cells, although we did not examine the basal levels of these proteins." (PMID 30558665, 2018). "The proliferation of the four studied pancreatic cancer cell lines was not influenced by S100A8, S100A9, S100A8/A9 and/or TGFβ1." (PMID 24670043, 2014).
diabetes (42 papers, 2006 to 2025). "It has been reported that HBV infection is closely associated with diabetes-related liver cirrhosis, where the accumulation of S100A8/A9 in patients with cirrhosis and diabetes activates NK cells through receptor for advanced RAGE-mediated p38 MAPK signaling." (PMID 40568596, 2025). "To investigate the underlying mechanism of high S100A8 and A9 expression in diabetic wounds, we used ex vivo skin cultures that we stimulated with typical diabetes-associated inflammatory and metabolic factors." (PMID 39337466, 2024). "Presence of high levels of S100A8/9 is also associated with the pathogenesis of diabetes and this protein complex can be used as a biomarker." (PMID 36653816, 2023). "Patients with S100A8/A9 values within the top quartile had a 2 times higher risk to develop a recurrent event compared to the lowest quartile, independently of diabetes, hypertension, previous CV disease, heart failure, and hsCRP." (PMID 24453429, 2013). "In simple linear regression analysis, the serum levels of S100A12 in RA patients were positively associated with ACPA, RF, history of diabetes, and serum levels of S100A8 and S100A9 (P < 0.05)." (PMID 19284577, 2009). "Thus, hepatitis viruses drive IFN-γ-mediated β-cell apoptosis through STAT3/IL-6/S100A8/A9 crosstalk, promoting insulin resistance and diabetes risk." (PMID 40918255, 2025). "Diabetes, through neutrophil-released S100A8/A9, also causes liver inflammation." (PMID 33195459, 2020). "HBV-induced liver cirrhosis patients exhibit elevated levels of S100A8/A9, natural killer (NK) cells, and interferon-gamma (IFN-γ) following STAT3 activation, a biomarker profile associated with diabetes development." (PMID 40918255, 2025). "Several S100 members, mainly S100A4 and S100A8/9, have been identified as key players in the pathogenesis of many types of cancer, as well as of several other disease conditions, including diabetes and other inflammatory diseases." (PMID 39493128, 2024). "Research has found that a large amount of S100A8 have been found in diabetes patients, and it has been used as a biomarker of diabetes." (PMID 37497233, 2023). "In various inflammation associated diseases, including diabetes mellitus, the levels of S100A8 (Calgranulin A), a small calcium binding protein also known as MRP8, used as a biomarker for diagnostic purpose owing to its secretion in a disease-specific manner." (PMID 36653816, 2023). "With regard to diabetes and the eye, systemic levels of the S100A8 and S100A9 protein strongly correlated with the severity of diabetic retinopathy in patients with type 2 diabetes." (PMID 38153746, 2023). "In line with their pleiotropic functions, S100A8 and S100A9 have been implicated in a variety of diseases, ranging from arthritis to diabetes and cardiovascular diseases." (PMID 35998224, 2022). "The cumulative research supports our findings and it becomes pertinent to propose S100A9/S100A8 a potent biomarker for tuberculosis and diabetes copathogenesis." (PMID 33156824, 2020). "In diabetes, we found that monocytosis is consequential of hyperglycemia-induced upregulation of plasma S100A8/A9." (PMID 31249530, 2019). "In frail subjects, similar to what has been observed in diabetes, excessive S100A8/A9‐mediated RAGE signaling could contribute to myelopoiesis, leukocytosis, and vascular dysfunction." (PMID 35166014, 2022). "S100A8/A9 provides an important first signal for inducing the hematopoietic response in the BM by directly interacting with RAGE on common myeloid progenitor cells in diabetes or through TLR-4-mediated mechanisms in obesity." (PMID 33282877, 2020). "S100A8/A9 circulating levels high were related to a persistent diabetes status post-BS." (PMID 31941045, 2020). "S100A8/A9 has been used as a biomarker of diabetes mellitus, and high levels of this protein complex may be associated with atherosclerosis in diabetic patients." (PMID 29942307, 2018).